NRG3 (neuregulin 3)
Diseases named in the same sentence as NRG3 in open-access papers (continued):
Sharing a sentence is not in itself a finding about the gene and the disease.
glioma (5 papers, 2013 to 2021). A benign or malignant brain and spinal cord tumor that arises from glial cells (astrocytes, oligodendrocytes, ependymal cells). "Compared to control brain, NRG3 is underexpressed in high grade gliomas and its sustained expression in good prognosis gliomas may reflect preservation of normal features by the tumor tissue." (PMID 23805239, 2013). "After constructing the risk model, we screened out the signature composed of five ATGs (BID, BAG1, PTK6, NRG3, MAP1LC3C) with the best prognosis prediction performance, indicating these five ATGs play an important role in glioma." (PMID 33768004, 2021). "The results showed that NRG1 (p=0.0045), NRG3 (p=0.0073) and NRG4 (p=0.026) were significantly related to survival in recurrent gliomas (all WHO grade), and NRG2 (p=0.031) and NRG3 (p<0.0001) were significantly related to survival in primary gliomas (all WHO grades)." (PMID 34054873, 2021). "Furthermore, NRG3 and NRG1 may serve as potential independent biomarkers in LGG and GBM in clinical applications, respectively, including glioma diagnosis and drug development." (PMID 34054873, 2021). "Upon looking into the copy number loss of NRG2, NRG3, and BTC in glioma cell lines from CCLE, we found that no copy number loss was observed across glioma cell lines for NRG2 and BTC and copy number loss of NRG3 occurred in approximately 12% of glioma cell lines." (PMID 29342193, 2018).
Hirschsprung disease (5 papers, 2014 to 2023). Hirschsprung disease (HSCR) is a congenital intestinal motility disorder that is characterized by signs of intestinal obstruction due to the presence of an aganglionic segment of variable extent in the terminal part of the colon. "Incidentally, NRG3 copy number and single nucleotide variants have been associated with Hirschsprung disease." (PMID 29045412, 2017). "A similar WES effort in Hirschsprung’s disease sequenced two affected (related) samples and also used pathway analysis to investigate the role of the neuregulin 3 (NRG3) gene in disease susceptibility." (PMID 24705293, 2014). "By acting on ErbB4, NRG3 promotes the development of Hirschsprung disease (HSCR)." (PMID 34484469, 2021). "CNV analysis on Hirschsprung disease (HSCR), also known as congenital intestinal aganglionosis, identified a novel candidate gene, NRG3, with an increased burden of intronic CNVs (both deletions and duplications) in patients." (PMID 37593442, 2023).
Alzheimer disease (4 papers, 2014 to 2024). A progressive, neurodegenerative disease characterized by loss of function and death of nerve cells in several areas of the brain leading to loss of cognitive function such as memory and language. "It has been reported that NRG3 is associated with the risk and age at onset of Alzheimer's disease." (PMID 34220946, 2021). "Ablation of NRG3 and ERBB4 leads to a reduction in the number of excitatory synapses on small parvalbumin-positive interneurons, altered short-term neuroplasticity, and disinhibition of the hippocampal network, which plays a critical role in intercellular communication in alzheimer’s disease." (PMID 38383423, 2024).
colon tumor (3 papers, 2016 to 2021). "SW48 cells (human colon cancer cell line containing WT KRAS) in PBS or PBS containing WSTF/NRG3 proteins (PBS+) were injected into 6- to 8-week-old female BALB/C mice." (PMID 27449290, 2016). "The appearance of WSTF/NRG3 in serum and urine correlates with a colon tumor carrying a KRASG12 mutant." (PMID 27449290, 2016). "Extracellular WSTF/NRG3 promotes the formation of colon tumors." (PMID 27449290, 2016). "The WSTF/NRG3 complex mediated cell–cell communication leads to the activation of oncogenic pathways of the surrounding normal colon cells and promotes the formation of colon tumor." (PMID 27449290, 2016). "Because colon cancer cells with wild type KRAS could be transformed by WSTF/NRG3, they would be not sensitive to the targeted inhibition of EGFR." (PMID 27449290, 2016). "In combination with NRG3, Williams-Beuren syndrome transcription (WSTF), a nonsecretory protein, activates oncogenesis of colon tumors." (PMID 34484469, 2021).
mental disorder (3 papers, 2017 to 2023). A disease that has its basis in the disruption of mental process. "Neuregulin 3 (NRG3) plays a key role in central nervous system development and is a strong candidate for human mental disorders." (PMID 28732471, 2017).
attention deficit hyperactive disorder (2 papers, 2020 to 2024). "NRG3 mutations, especially those that result in overexpression, are thought to cause symptoms synonymous to those seen in attention deficit hyperactive disorder (ADHD), as well as broader cognition disorders." (PMID 38369520, 2024).
Developmental delays (2 papers, 2017 to 2024). "Developmental delays and craniofacial anomalies associated with a loss of genetic material at the NRG3 locus, accompanied by a gain of material at the DLGAP1 site, have also been reported." (PMID 29045412, 2017).
Insulin resistance (2 papers, 2017 to 2022). Increased resistance towards insulin, that is, diminished effectiveness of insulin in reducing blood glucose levels. "According to the GWAS catalog, NRG3 polymorphisms are genetically associated with various diseases, including cancer, insulin resistance, and tau protein formation." (PMID 36704746, 2022).
Obesity (2 papers, 2017 to 2020). Accumulation of substantial excess body fat. "SNPs from genes associated with alcohol dependence (ESR1) and obesity traits (RGS7, NRG3 and ESR1) were observed among Western reported dietary pattern score-associated SNPs." (PMID 28644415, 2017).
psychotic disorder (2 papers, 2021 to 2024). An abnormal condition of the mind that involves a loss of contact with reality. "Nrg3 KO mice also exhibit behaviors consistent with psychotic disorders." (PMID 34072341, 2021).
astrocytomas (1 paper, 2023). "In TCGA data, NRG3 was concomitantly deleted with PTEN in 30 out of 34 (88%) IDHmut astrocytomas cases with PTEN loss, and in all (n = 197) IDHwt GBs with PTEN loss." (PMID 37932833, 2023). "In our TCGA data analysis, NRG3 showed reduced expression in grade 4 tumors, and low expression was associated with worse OS in IDHmut astrocytomas both in univariate and multivariate analysis, consistent with previous reports on its prognostic role in diffuse glioma in general." (PMID 37932833, 2023). "Furthermore, low NRG3 expression (below 7.7 i.e. mean expression in the whole TCGA diffuse glioma cohort) was associated with worse survival in the entire diffuse glioma cohort and within IDHmut astrocytomas (p < 0.0001, log-rank test)." (PMID 37932833, 2023). "In the GLASS data from matched IDHmut astrocytoma tumors of patients with tumor progression to grade 4 (n = 33), NRG3 was hemizygously deleted in 14 cases upon progression to grade 4, 13 of which were concomitant with a PTEN loss." (PMID 37932833, 2023). "In the ICGC WGS data, additional rearrangements in NRG3 (one GB) or in the genomic neighborhood of NRG3 (one grade 2 and one grade 4 IDHmut astrocytoma, one GB) were detected." (PMID 37932833, 2023). "In TCGA IDHmut astrocytomas, 9 of these genes, including NRG3, had significantly (p < 0.05, one-sided Wilcoxon rank-sum test, log2FC < − 1) lower expression in cases with hemizygous loss of gene, compared to neutral copy number." (PMID 37932833, 2023). "In TCGA diffuse glioma data (n = 595), NRG3 RNA expression decreased with tumor grade in IDHmut astrocytomas and oligodendrogliomas (p < 0.05, Wilcoxon rank-sum test), especially upon progression to grade 4 astrocytomas (p < 0.0001, Wilcoxon rank-sum test)." (PMID 37932833, 2023). "In IDHmut astrocytomas, hemizygous NRG3 losses were significantly more frequent in grade 4 than in grade 2–3 tumors (p = 1.7*10–4, Fisher’s exact test) and were associated with decreased NRG3 expression." (PMID 37932833, 2023). "Similarly, the downregulation of NRG3 was stronger than for PTEN in TCGA IDHmut astrocytomas with increasing grade and upon hemizygous gene deletion." (PMID 37932833, 2023).
cocaine-dependent (1 paper, 2022). "A GWAS metanalysis of four samples of subjects with European ancestry (2085 cocaine-dependent patients and 4293 controls) found suggestive associations (P < 1E−05) of several SNPs with cocaine dependence, being rs3075660 in the NRG3 gene the most significant one." (PMID 34453125, 2022).
colorectal adenoma (1 paper, 2018). An adenoma that arises from the colon or rectum. "Using genome-wide DNA methylation analysis, we identified novel aberrant methylation profiles of genes including HLX, CUX2, MKX, NRG3 and PDGFRA associated with the colorectal adenoma-carcinoma sequence progression." (PMID 29945573, 2018).
diffuse astrocytoma (1 paper, 2023). A low-grade (WHO grade II) astrocytic neoplasm. "We also linked NRG3 to tumor progression and tumor aggressiveness in diffuse astrocytomas." (PMID 37932833, 2023). "Further studies are needed to better understand the functional role of NRG3 in diffuse astrocytomas." (PMID 37932833, 2023).
endometriosis (1 paper, 2021). The growth of functional endometrial tissue in anatomic sites outside the uterine body. "Additionally, we identified some candidate genes linked to reproductive diseases, such as NRG3 and XRCC3 for ovarian cancer, and BAG5, CKB and XRCC3 for endometriosis." (PMID 33477586, 2021).
epilepsy (1 paper, 2023). A brain disorder characterized by episodes of abnormally increased neuronal discharge resulting in transient episodes of sensory or motor neurological dysfunction, or psychic dysfunction. "Therefore, we speculate that this signaling pathway of astrocytes may act as a protective function in epileptic pathology and NRG3 may be a new target for anticonvulsant drugs in epilepsy." (PMID 37189441, 2023).
head and neck squamous cell carcinoma (1 paper, 2021). A squamous cell carcinoma that arises from any of the following anatomic sites: lip and oral cavity, nasal cavity, paranasal sinuses, pharynx, larynx, and salivary glands. "NRG3 was recently identified as a prognostic index for inpatients with head and neck squamous cell carcinoma." (PMID 34220946, 2021).
heart failure (1 paper, 2022). Inability of the heart to pump blood at an adequate rate to meet tissue metabolic requirements. "Notably, mouse studies identified that cardiomyocyte specific loss of NRG3 receptors (ErbB2 and ErbB4) results in spontaneous heart failure suggesting a potential role for NRG3 in regulating cardiac homeostasis." (PMID 35959412, 2022).
Intellectual disability (1 paper, 2022). "Four genes each were associated with human educational attainment and intellectual disability, of which CHD2, NRG3 and LRRC7 were associated with both." (PMID 36056154, 2022).
metabolic syndrome (1 paper, 2016). A cluster of metabolic risk factors for CARDIOVASCULAR DISEASES and TYPE 2 DIABETES MELLITUS. "Furthermore, a number of genes within the RNO16 differential segment associated with metabolic syndrome components in human studies showed polymorphisms between SHR and BN-Lx (including Lpl, Nrg3, Pbx4, Cilp2, and Stab1)." (PMID 27031336, 2016).
neuroblastoma (1 paper, 2014). Neuroblastoma (NB) is the most common solid, extracranial childhood tumor. "SK-N-BE neuroblastoma cells, which show high expression of the ErbB4 receptor, were exposed to this CM and NRG3-specific ErbB4 activation was observed after appropriate inmmunoprecipitation and immunoblotting procedures." (PMID 25268740, 2014).
renal fibrosis (1 paper, 2024). A final common manifestation of a wide variety of chronic kidney diseases characterized by glomerulosclerosis and tubulointerstitial fibrosis. "Although the literature does not provide direct evidence of the association of NRG3 and renal fibrosis or disease progression, numerous publications have reported the involvement of ERBB in various renal diseases." (PMID 38768139, 2024).
tauopathy (1 paper, 2023). Neurodegenerative disorders involving deposition of abnormal tau protein isoforms (tau proteins) in neurons and glial cells in the brain. "The impact of tau pathology and Dap12 deletion on TEMM2 or NRG3 was further confirmed by Western blot analysis, illustrating increased levels of TEMM2 and NRG3 proteins in the cortical tissue of tauopathy-afflicted brains, which is mitigated in DAP12 loss." (PMID 37961627, 2023).
trigeminal neuralgia (1 paper, 2024). Trigeminal neuralgia is a nerve disorder that causes a stabbing or electric-shock-like pain in parts of the face. "Elevated expression levels of microRNAs (miR-155-5p) targeting NRG3 were observed among individuals with trigeminal neuralgia, another chronic neuropathic pain condition, compared to healthy controls, suggesting possible microRNA involvement in chronic neuropathic pain development." (PMID 39258169, 2024).
tumor (13 papers, 2004 to 2025). "Detailed analyses of structural alterations and CNVs of this tumor revealed a gain at the NRG3 gene, a ligand for ERBB4 and ERBB3 receptors, that was previously shown to play a role in ERBB pathway activation." (PMID 30499260, 2019). "It is noteworthy that the appearance of WSTF and NRG3 in serum was earlier than any detectable tumor mass." (PMID 27449290, 2016). "Given the results that serum WSTF/NRG3 correlates with tumor formation, we sought to explore whether detection of the serum and urine WSTF/NRG3 could be developed into a clinical diagnostic test." (PMID 27449290, 2016). "Analysis of clinical samples validated the overexpression of the 4 genes (SQSTM1, BIRC5, NRG3, and CXCR4) in tumor tissues relative to paired normal tissues, consistent with bioinformatic findings." (PMID 34484469, 2021). "In addition, five other genes, including TBPL1, USP28, NRG3, PPM1L, and RGR, were regulated by eRNAs expressed only in LGG tumor tissue; whereas SEMA4G was regulated by LGG-specific seRNAs." (PMID 35299740, 2022). "Macrophages altered by tumor CCL5 expression and EVs have increased expression of several genes known to drive invasion and metastasis, including OPN, SLPI, HGF, and NRG3." (PMID 34298673, 2021). "Interestingly, CCL7, CCL19, CXCL7, NRG3, SLPI, OPN, and HGF in macrophages are upregulated in response to increased tumor CCL5 expression." (PMID 34298673, 2021). "From the fifth day after injection, WSTF and NRG3 could be detected in serum samples of the PBS+ group and the levels were increased along with tumor growth." (PMID 27449290, 2016). "This revealed that tumor cells in MBMs not only exhibited significantly upregulated tumorigenesis and maintenance genes (e.g., MET and TBX2), but also expressed neural differentiation markers (e.g., NRG3, NELL1, NCAM1, ADNP) and cell adhesion molecules (e.g., CDH1, PRKCA)." (PMID 41284647, 2025).
psychiatric disorder (9 papers, 2014 to 2024). A disorder characterized by behavioral and/or psychological abnormalities, often accompanied by physical symptoms. "Since NRG3 is primarily expressed in the central nervous system and has been linked to psychiatric disorders in previous studies, we focused our attention exclusively on NRG3 in downstream experiments." (PMID 37432876, 2023). "Genes previously implicated in mood and psychiatric disorders as well as chronic stress (e.g., NRG3) also were identified." (PMID 32843619, 2020). "Less information is available on the biological functions and possible relevance of Neuregulin 3 (NRG3) for mental illness." (PMID 24976857, 2014).
cancer (7 papers, 2016 to 2024). A tumor composed of atypical neoplastic, often pleomorphic cells that invade other tissues. "We were interested to investigate the binding of NRG3 with WSTF in other human cancer cell lines and found that the association between NRG3 and WSTF could be unique in colon cells." (PMID 27449290, 2016). "The NRG3, in the larger neuregulin gene family, induces proliferation, migration, differentiation, and survival or apoptosis of cancer cells." (PMID 34484469, 2021). "Many drugs which could inhibit NRG3-ErbB4 signaling specifically already exist, although usage is limited to cancer treatment." (PMID 39258169, 2024). "NEO cells from parasympathetic HN-PG expressed NRG3 and LEF1, the latter identified as a cancer checkpoint in HN-PG25." (PMID 36271074, 2022).
neurological disorders (3 papers, 2014 to 2026). "As mentioned, NRG3 has been implicated in severe neurological disorders with developmental origins." (PMID 35391799, 2022). "Despite our expanding knowledge of genetic involvement of NRG3 in neurological disorders, little is known about the neurodevelopmental mechanisms of risk." (PMID 25093331, 2014).
infection (2 papers, 2016 to 2021). The state of being infected such as from the introduction of a foreign agent such as serum, vaccine, antigenic substance or organism. "While it has not been explored previously in T. gondii infection, the significant decrease in NRG3 may be partly responsible for some infection-induced neuropathology such as increases in extracellular glutamate concentration and excess neuronal firing." (PMID 33816350, 2021).
gastrointestinal tumors (1 paper, 2021). "Expression of the 4 autophagy-related genes (SQSTM1, BIRC5, NRG3, and CXCR4) can accurately predict the prognosis of gastrointestinal tumors in Asian patients." (PMID 34484469, 2021).
neurodegenerative disease (1 paper, 2023). A disorder of the central nervous system characterized by gradual and progressive loss of neural tissue and neurologic function. "Nrg3 has been demonstrated to affect dendritic and axonal growth, which may be broadly involved in the development of neurodegenerative diseases." (PMID 37505566, 2023).
NRG3 also shares sentences with these, for which no sentence is quoted: depression (5 papers); autism (4); autism spectrum disorder (2); myeloma (2); neurodevelopmental disorder (2); nicotine addiction (2); alcohol dependence (1); amyotrophic lateral sclerosis (1); behavioral disorders (1); bladder cancer (1); brain disorder (1); colon cancer (1); cytomegalovirus infection (1); diabetes (1); eating disorder (1); endometrial cancer (1); oligodendroglioma (1); ovarian carcinoma (1); Parkinson disease (1); renal diseases (1); reproductive diseases (1); schizoaffective disorder (1).